MAPK12 (mitogen-activated protein kinase 12)
Description:
Serine/threonine kinase which acts as an essential component of the MAP kinase signal transduction pathway. MAPK12 is one of the four p38 MAPKs which play an important role in the cascades of cellular responses evoked by extracellular stimuli such as pro-inflammatory cytokines or physical stress leading to direct activation of transcription factors such as ELK1 and ATF2. Accordingly, p38 MAPKs phosphorylate a broad range of proteins and it has been estimated that they may have approximately 200 to 300 substrates each. Some of the targets are downstream kinases such as MAPKAPK2, which are activated through phosphorylation and further phosphorylate additional targets. Plays a role in myoblast differentiation and also in the down-regulation of cyclin D1 in response to hypoxia in adrenal cells suggesting MAPK12 may inhibit cell proliferation while promoting differentiation. Phosphorylates DLG1. Following osmotic shock, MAPK12 in the cell nucleus increases its association with nuclear DLG1, thereby causing dissociation of DLG1-SFPQ complexes. This function is independent of its catalytic activity and could affect mRNA processing and/or gene transcription to aid cell adaptation to osmolarity changes in the environment. Regulates UV-induced checkpoint signaling and repair of UV-induced DNA damage and G2 arrest after gamma-radiation exposure. MAPK12 is involved in the regulation of SLC2A1 expression and basal glucose uptake in L6 myotubes; and negatively regulates SLC2A4 expression and contraction-mediated glucose uptake in adult skeletal muscle. C-Jun (JUN) phosphorylation is stimulated by MAPK14 and inhibited by MAPK12, leading to a distinct AP-1 regulation. MAPK12 is required for the normal kinetochore localization of PLK1, prevents chromosomal instability and supports mitotic cell viability. MAPK12-signaling is also positively regulating the expansion of transient amplifying myogenic precursor cells during muscle growth and regeneration.
Synonyms: MAPK 12; ERK-6; ERK6; SAPK3; PRKM12; p38gamma; SAPK-3; ERK3
Tractability: Small molecule: a structure with a bound ligand is known; a high-quality ligand is known; it belongs to a druggable protein family. PROTAC: it is named in the literature on targeted protein degradation; UniProt records ubiquitination sites on it; ubiquitination databases record sites on it; a small molecule that binds it is known.
Target class: Protein Kinase; CMGC protein kinase group; CMGC protein kinase p38 subfamily; CMGC protein kinase MAPK family; Enzyme; Kinase
Chemical probes: DORAMAPIMOD (high quality)
Gene: Protein-coding gene on chromosome 22 (50,245,450 to 50,261,734, reverse strand). Ensembl gene ENSG00000188130.
Subcellular location: Cytoplasm; Nucleus; Mitochondrion
Subcellular location (Human Protein Atlas): Nuclear speckles; Cytosol
Pathways (Reactome):
Signal Transduction: Negative regulation of MAPK pathway; VEGFA-VEGFR2 Pathway; p38MAPK events
Developmental Biology: Myogenesis
Immune System: NOD1/2 Signaling Pathway
Organelle biogenesis and maintenance: Activation of PPARGC1A (PGC-1alpha) by phosphorylation
Gene Ontology:
Molecular function: magnesium ion binding; protein binding; protein serine kinase activity; protein serine/threonine kinase activity; MAP kinase activity; peptidase activator activity; ATP binding; protein kinase activity
Biological process: MAPK cascade; myoblast differentiation; intracellular signal transduction; muscle organ development; positive regulation of muscle cell differentiation; regulation of cell cycle; signal transduction; signal transduction in response to DNA damage; cellular response to stress; negative regulation of cell cycle
Cellular component: cytosol; nucleoplasm; cytoplasm; mitochondrion; nucleus
Genetic constraint (gnomAD): Loss-of-function variants: 45 observed, 41.61 expected, observed/expected ratio (o/e) 1.08, 90% interval 0.85 to 1.39. The synonymous counts are far from expectation, so gnomAD's model fits this gene poorly and the ratio says little. Missense variants: 494 observed, 429.77 expected, observed/expected ratio (o/e) 1.15, 90% interval 1.07 to 1.24. Synonymous variants: 228 observed, 184.25 expected, observed/expected ratio (o/e) 1.24, 90% interval 1.11 to 1.38.
Homologues: Orthologues: macaque MAPK12 (99% identical), chimpanzee MAPK12 (97% identical), dog MAPK12 (95% identical), rat Mapk12 (94% identical), mouse Mapk12 (93% identical), guinea pig MAPK12 (92% identical), pig MAPK12 (92% identical), rabbit MAPK12 (92% identical), tropical clawed frog mapk12 (76% identical), zebrafish mapk12b (69% identical), zebrafish mapk12a (68% identical), Caenorhabditis elegans pmk-1 (55% identical), and 10 more. Paralogues in human: MAPK13 (65% identical), MAPK11 (61% identical), MAPK14 (61% identical), MAPK10 (47% identical), MAPK9 (46% identical), MAPK8 (46% identical), MAPK1 (39% identical), MAPK3 (39% identical), MAPK7 (38% identical), NLK (35% identical), MAPK6 (34% identical), MAPK15 (34% identical), and 7 more.